ABCG8 (ATP binding cassette subfamily G member 8)
Diseases named in the same sentence as ABCG8 in open-access papers (continued):
Sharing a sentence is not in itself a finding about the gene and the disease.
sitosterolemia (continued). "At virtually the same time, independent groups identified individuals in multiple kindreds harboring nonsense mutations in either ABCG5 or ABCG8 with sitosterolemia, but not their unaffected family members." (PMID 33807969, 2021). "The ABCG8 KO background was chosen because of the manifestation of phytosterolemia." (PMID 31317217, 2020). "Therefore, genetic testing of the ABCG5 and ABCG8 genes will play a crucial role in the accurate and early diagnosis of sitosterolemia." (PMID 33014402, 2020). "Two genes, ABCG5 and ABCG8, comprise the STSL and mutations in either cause sitosterolemia." (PMID 16507104, 2006). "However, as no other ABCG5 or ABCG8 mutations were identified, the presence of sitosterolemia (autosomal recessive inheritance) was rejected." (PMID 35741760, 2022). "Sitosterolemia (STSL) is a rare, autosomal recessive disease caused by mutations in the genes ABCG5 (encoding sterol-1) and ABCG8 (encoding sterol-2) located on chromosome 2p21." (PMID 35743896, 2022). "One of the possible explanations is that deletion in ABCG8 reduces biliary cholesterol secretion, and excretion of sterols into the bile seems pivotal for their accumulation, as liver transplantation in the patient with sitosterolemia led to complete normalization of the plant sterols levels." (PMID 35096999, 2021). "In the structurally similar ABCG5/ABCG8 asymmetric mammalian lipid transporter, an R263Q mutation in the long linker connecting transmembrane helix 1 (TMH-1) of ABCG8 to the nucleotide-binding domain (NBD) has a loss-of-function phenotype resulting in sitosterolemia." (PMID 31757931, 2020). "Sitosterolemia (OMIM#210250), is a very rare inherited sterol storage disease caused by mutations in the adenosine triphosphate-binding cassette (ABC) transporter genes ABCG5 and ABCG8, which are located on chromosome 2p21 and expressed at the membrane of enterohepatic cells." (PMID 25424010, 2014). "Mutations in two adjacent ATP-binding cassette transporters, ABCG8 (sterolin-2) and ABCG5 (sterolin-1) that regulate sterol transport at the apical surface of hepatocytes and enterocytes have been identified in patients with sitosterolemia." (PMID 23675242, 2011). "Thus, the remaining 1 potential sitosterolemia patient and 12 possible heterozygote carriers of ABCG5 or ABCG8 variants could not receive molecular confirmation." (PMID 32845916, 2020). "Based upon the defects in sitosterolemia, ABCG5 and ABCG8 serve specifically to exclude non-cholesterol sterol entry at the intestinal level and are involved in sterol excretion at the hepatobiliary level." (PMID 15383151, 2004). "In sitosterolemia, lack of ABCG5/ABCG8 function leads to significantly greater absorption of dietary cholesterol and sitosterol and an increased incidence of cardiovascular events independent of plasma LDL-C levels, suggesting that sitosterol itself may be contributing to atheroma formation." (PMID 22649448, 2012).
gallstones (34 papers, 2009 to 2025). Solid crystalline precipitates in the biliary tract, usually formed in the gallbladder, resulting in the condition of cholelithiasis. "The genes most strongly associated with the risk of gallstone formation are the ABCG5/ABCG8 genes encoding the transmembrane cholesterol transporter from the large group of ATP-binding cassette transporters family." (PMID 40149408, 2025). "For instance, the ATP-binding cassette subfamily G member 8 (ABCG8) rs11887534 variant independently increases gallstone risk by impairing biliary cholesterol excretion – an effect unrelated to BMI." (PMID 40171569, 2025). "The combined risk of gallstones conferred by the presence of one of the pathogenic variants of the ABCG8 or UGT1A1 genes was estimated at 20%." (PMID 40149408, 2025). "In this regard, a genetic variant in the ABCG8 gene (variant rs11887534 or D19H) has been associated with a higher gallstone development through cholesterol hypersecretion and cholesterol supersaturation in the bile." (PMID 35207722, 2022). "Genetic studies identified that a point mutation Asp19His in ABCG8 increases risk of gallstones, which is formed by supersaturated cholesterol in bile." (PMID 33953337, 2021). "The current study with a relatively large sample size further confirms the role of ABCG8 in gallstone predisposition among Taiwanese." (PMID 34906072, 2021). "In mice and humans, this polymorphism promoted gallstone formation by increasing the expression of ABCG8, consequently enhancing biliary cholesterol production and buildup while decreasing dietary cholesterol absorption." (PMID 34906072, 2021). "Although several studies have been conducted on gallstones in Taiwan, only a few of them considered the role of the ABCG8 variant." (PMID 34906072, 2021). "Genome-wide association studies (GWAS) and meta-analyses of GWAS revealed the ABCG8 rs11887534 variant as the most common genetic determinant of gallstones in humans." (PMID 34906072, 2021). "ATP-binding cassette transporter (ABCG8) which regulates cholesterol efflux from the liver has been reported as the main genetic susceptibility factor for gallstones." (PMID 34906072, 2021). "In summary, both the presence of gallstones and the ABCG8 polymorphism D19H were related to diminished cholesterol absorption but the polymorphism did not affect ileal expression of ABCG8, suggesting a gain-of-function of the mutated transporter." (PMID 23406058, 2013). "Third, in the cohort of gallstone carriers and controls the D19H polymorphism of the ABCG8 gene was associated with a low cholesterol absorption but not with altered de novo synthesis." (PMID 23406058, 2013). "The polymorphism D19H of sterol exporter ABCG8 was associated with gallstones in various populations and different ethnic groups." (PMID 23406058, 2013). "Four other variants, which were in nearly complete linkage disequilibrium, exhibited genome-wide significant associations with gallstone disease history, and the ABCG8 rs11887534 variant showed a trend of superiority for gallstone disease history in a nested logistic regression model (p = 0.074)." (PMID 36981027, 2023). "Furthermore, 20.8% of the Swedish twins with gallstone disease carried at least one ABCG8 D19H allele, a gallstone candidate gene, which was linked with a 2.54-fold increased risk of gallstone disease." (PMID 36232007, 2022). "Similarly, in a study among Indians, the association of gallstone with the ABCG8 rs11887534 polymorphism was more prominent in women." (PMID 34906072, 2021). "Furthermore, carriers of CG genotype of ABCG8 rs11887534 showed higher risk of gallstones, as well as gallbladder and bile duct cancer compared with carriers of the GG genotype." (PMID 23691293, 2013). "However, overweight carriers of the ABCG8 19H risk allele displayed a higher OR than normal weight gallstone carriers." (PMID 23406058, 2013).
gallstones (continued). "The analysis of twin pairs from The Swedish Twin Registry showed that genetic factors are estimated to account for about 25% of gallstone risk and that twins carrying a heterozygous or homozygous ABCG8 D19H genotype have a significantly increased risk of gallstone disease." (PMID 23691293, 2013). "In our previous study, we found higher levels of hepatic ABCG5/ABCG8 and LXRa mRNA in gallstone patients, which could cause higher amounts of cholesterol to be delivered into the bile." (PMID 20144195, 2010). "Among four ABCG5/G8 variants associated with gallstone disease history, only two were nonsynonymous [ABCG5 R50C (rs6756629) and ABCG8 D19H (rs11887534)]." (PMID 36981027, 2023). "FMO3 loss or gain-of-function experiments in cholesterol fed mice demonstrated that TMAO induces ABCG5 and ABCG8 expression, and presumably increases bile cholesterol content to drive gallstone formation." (PMID 34445033, 2021). "To date, it has been discovered that the CYP27A1, LXR, PPAR-α, ABCG8 and ABCB11 genes involved in lipid metabolism predispose an individual to gallstone formation." (PMID 32615989, 2020). "After administration of the LXRα agonist, the ABCG5 and ABCG8 expression levels were further increased, and the gallstone formation was also promoted." (PMID 32382260, 2020). "Increased hepatic expression of ABCG5 and ABCG8 mRNA in gallstone patients has been reported, which represents the main defect leading to hyper-secretion of cholesterol in hepatocyte." (PMID 27203212, 2016). "What is more, research suggests that FXR and the heterodimer ABCG5/ABCG8 are possible determinants of cholesterol gallstone formation in mice via quantitative trait locus analysis." (PMID 25107305, 2014). "Our multi-analytic approach revealed that the combination of genotypes of respective polymorphisms as ESR1 IVS1-397 variant, ABCG8 145 variant, ESR1 IVS1-351 variant and ADRB3 190 variant pose a significant risk for developing gallstone." (PMID 23577061, 2013). "In a previous study, we observed that Chinese gallstone patients had an increased hepatic ABCG5/ABCG8 expression." (PMID 20144195, 2010). "Therefore, ABCG5 and ABCG8 are thought to play crucial roles in gallstone formation by regulating cholesterol secretion." (PMID 37310967, 2023). "We also observed that the association of ABCG8 and TRAF3 variants with GBC was significant only when GBC samples were compared to gallstone-free individuals, indicating that the risk contribution to GBC was explained by the presence of gallstones." (PMID 30692554, 2019). "In the same way D19H variant of ABCG8 was attributed in gallstone formation neither T400K of ABCG8 nor Q604E of ABCG5." (PMID 29511480, 2017). "ABCG8 encodes a cholesterol transporter that has been implicated in CAD and in gallstone formation." (PMID 24988487, 2014). "In our study carriers of p.D19H were characterised by significantly reduced intestinal cholesterol absorption irrespective of the presence or absence of gallstones and the polymorphism did not affect intestinal ABCG8 expression." (PMID 23406058, 2013). "The distinct up-regulation of genes Abcg5 and Abcg8 might implicate hypersecretion of cholesterol into bile and lead to gallstones formation." (PMID 19835623, 2009). "To date, the xenobiotic substrates of Abcg5 and Abcg8 have been used for regulating gallstones formation and treatments of cardiovascular disease, whereas the limited protective mechanism may not confer the expected reduction in cardiovascular risks in hypercholesterolemic patients." (PMID 19835623, 2009). "Our study indicates that MIC-1 influences gallstone formation by increasing AMPK phosphorylation, reducing CYP7A1 and HMGCR expression, and increasing ABCG5 and ABCG8 expression." (PMID 37310967, 2023). "Second, the ileal expression of the sterol transporters ABGG5, ABCG8 and NPC1L1 as well as of their relevant transcription factors is similar between gallstone carriers and controls." (PMID 23406058, 2013).
gallstones (continued). "Abca1, Abcg5 and Abcg8 belong to the family of ABC transporters, which can mediate secretion of excessive cholesterol into bile and play important roles in consequent gallstones or atherosclerosis." (PMID 19835623, 2009). "Therefore, the present study demonstrates a novel role of miRNA-223 in the gallstone formation by targeting ABCG5 and ABCG8 and elevating miRNA-223 would be a potentially novel approach to overcome the sternness of cholesterol gallstone disease." (PMID 34803510, 2021). "Thus, increasing the expression levels of ABCG8, ABCB11, CYP7A1 and CYP27A1 or decreasing the levels of LXR and PPAR-α can stimulate bile acid secretion and efficiently facilitate gallstone dissolution to reverse damage to the hepatocytes." (PMID 32615989, 2020). "In mice, it has been reported that there is an increased propensity to cholesterol crystallization and gallstone formation in bile following the activation of hepatic LXR and direct upregulation of the major cholesterol efflux transporters ABCG5 and ABCG8 on the canalicular membrane of hepatocyte." (PMID 23691293, 2013). "Similarly, patients with gallstones had increased ABCG5 and ABCG8 levels and decreased BSEP levels." (PMID 34445033, 2021). "Although some LXR targets in mice are not conserved in humans, these results revealed that LXRα promoted cholesterol transport from the liver to bile and gallstone formation by upregulating ABCG5 and ABCG8 expression levels, which might provide a new direction in the treatment of gallstones." (PMID 32382260, 2020). "Regarding sterol exporter ABCG8 and ABCG5, no significant changes in expression were apparent when stratified according to gallstones, also not within the different weight groups." (PMID 23406058, 2013). "Furtherly, in a small group of Chinese non-obese normolipidemic gallstone patients, the upregulation of ABCG5/ABCG8 in gallstone patients is mediated by increased LXRalpha possibly, may contribute to the cholesterol supersaturation of bile and the formation of gallstone." (PMID 25107305, 2014).
Hypercholesterolemia (21 papers, 2018 to 2026). An increased concentration of cholesterol in the blood. "A small part has pathogenic variants in ABCG5/ABCG8 in heterozygosity that can cause hypercholesterolemia and should be further investigated." (PMID 38122934, 2023). "In fact, studies performed widely have reported pathogenic ABCG5/ABCG8 variants to be associated with hypercholesterolemia." (PMID 38122934, 2023). "Meanwhile, ABCG8 deficiency had been shown to cause the failure of biliary cholesterol secretion, whereas its overexpression attenuated hypercholesterolemia and decreased atherosclerotic lesions by as much as 70% in susceptible mice." (PMID 36292250, 2022). "Human mutations in ABCG5 and ABCG8 contribute to the autosomal recessive β-sitosterolemia, a metabolic lipid disorder that causes hypercholesterolemia due to overabsorption of dietary sterols." (PMID 34884779, 2021). "Among compound heterozygotes D19H/T400K of the ABCG8 gene (rs11887534 and rs4148217), there is a higher risk of cardiovascular diseases among patients with hypercholesterolemia." (PMID 31795497, 2019). "Therefore, targeted gene sequencing analysis was performed using custom panels focusing on the exome regions of 21 lipid-associated genes, including ABCG5, ABCG8, and familial hypercholesterolemia-causing genes (LDL receptor, LDLRAP1, PCSK9, and apolipoprotein B)." (PMID 38338819, 2024). "Also, ABCG8 gene polymorphism may contribute to the rapid onset of CAD in patients suffering from familial hypercholesterolemia." (PMID 33829027, 2021). "Functional studies showed that variant can cause deletion of exon 8 in human ABCG5, and disruptions of ABCG5/ABCG8 genes recapitulated the occurrence of hypercholesterolemia and large platelets in rats." (PMID 34880906, 2021). "Saccharomyces boulardii CNCM I-745 significantly reduced the expression of ABCG5 and ABCG8 in hypercholesterolemia and increased the expression of HMG CoA-R gene." (PMID 33005189, 2020). "F. Briand fed hypercholesterolemia hamsters with Saccharomyces boulardii CNCM I-745, and CNCM I-745 significantly reduced the expression of ABCG5 and ABCG8 in hypercholesterolemia and increased the expression of HMG CoA-R gene (encoding a rate-limiting enzyme of cholesterol synthesis)." (PMID 33005189, 2020). "In Spanish patients with hypercholesterolemia, Asn578Ser (rs146534033), Gly288Cys (rs139264483), Arg198Glu (rs141828689), Gly269Arg (rs552803459), and Asn296Ser (rs552803459) in ABCG5 and Gly512Arg (rs376069170) in the ABCG8 gene have been detected." (PMID 31795497, 2019).
atherosclerosis (16 papers, 2009 to 2025). A disease characterized by the build-up of fatty material and calcium deposition in the arterial wall resulting in partial or complete occlusion of the arterial lumen. "Furthermore, a study on the mouse has shown that over-expression of ABCG5 and ABCG8 decreases diet-induced atherosclerosis, in association with reduced liver and plasma cholesterol levels." (PMID 22682430, 2012). "In atherosclerosis, the downregulation of FXR results in reduced expression of cholesterol transport proteins (ABCG5/ABCG8), ultimately affecting cholesterol efflux and causing cholesterol accumulation." (PMID 39781461, 2025). "These genes are involved in cholesterol metabolism (Abca1, Abcg8, Abcg5, Lpl, Cyp7a1, and Pltp), lipid and atherosclerosis (Abca1, Il1b, Ccl2, and Abcg1), bile secretion (Abcg8, Abcg5, and Cyp7a1), and IL-17 signaling pathway (Ccl7, Il1b, and Ccl2)." (PMID 37301941, 2023). "For instance, the ABCG8 gene variant rs6544713, T allele, has been associated with elevated LDL concentrations, which can contribute to conditions such as atherosclerosis and, eventually, coronary artery disease." (PMID 38026570, 2023). "Some studies have shown that ABCA1 and ABCG8 in the liver can prevent atherosclerosis by enhancing HDL biogenesis and hepatic cholesterol excretion." (PMID 27869741, 2016). "Some studies have assessed the respective roles of liver ABCA1 and ABCG8 in preventing atherosclerosis by promoting HDL biogenesis and hepatic cholesterol excretion." (PMID 26318157, 2015). "In the case that ABCG5/ABCG8 transports vitamin K2, defects in vitamin K2 transport by ABCG5/ABCG8 may be associated with the progression of atherosclerosis in addition to cholesterol transport impairment." (PMID 36839356, 2023). "The main difference in frequency was observed for ABCG8 rs4299376, which is consistent with previous findings indicating that a common single polymorphism in ABCG5/8 modulates plasma lipid concentrations in FH patients and influences atherosclerosis risk." (PMID 32942679, 2020). "In our study, the lower ABCG8 and ABCG5 expression in the SUS individuals may be at least partially responsible for the greater susceptibility of this strain to diet-induced atherosclerosis." (PMID 22682430, 2012). "Studies show that the activation of LXRα, one of the LXRs, attenuates the atherosclerosis formation by an increase in expression of cholesterol efflux transporters ABCA1 and ABCG1 in macrophages, and excretion transporters ABCG5 and ABCG8 in enterocytes." (PMID 27399689, 2016). "Thus, overexpression of GATA4 enhances hepatic expression of Abcg5 and Abcg8, and cholesterol excretion to the bile in L-Bmal1−/−Apoe−/− and Bmal1fl/flApoe−/− mice, while reducing MTP expression and atherosclerosis." (PMID 27721414, 2016). "Expression of ABCG5 (control diet) and ABCG8 (regardless of dietary treatment) and expression of HMGCR, FDFT1 and SQLE (regardless of dietary treatment) were significantly higher in the atherosclerosis-resistant than in the atherosclerosis-susceptible strain." (PMID 22682430, 2012).